LEP (leptin)
Diseases named in the same sentence as LEP in open-access papers (continued):
Sharing a sentence is not in itself a finding about the gene and the disease.
Obesity (continued). "In addition, the expression of Atp6v0a1 is highly elevated in multiple models of obesity including high-fat diet (HFD) fed mice and leptin deficient (ob/ob) mice fed either normal chow or HFD." (PMID 36042358, 2022). "Indeed, not only does it inhibit diet-induced obesity in mice by improving insulin and leptin signaling, but also slows the growth rate of breast tumors and reduces the possibility of cancer metastasis in the lungs." (PMID 35806030, 2022). "Increased plasma leptin levels found in obesity may reflect a high fat mass and partial resistance to leptin." (PMID 35204231, 2022). "Thus, maintaining optimal body fat levels is the best way to ensure physiological leptin levels and control excessive appetite and the development of obesity." (PMID 35806019, 2022). "Moreover, the increased SOCS3 in the hypothalamus in turn suppresses JAK2/STAT3 signaling pathway, which forms leptin resistance, leading to hyperleptinemia and obesity." (PMID 36270984, 2022). "Interestingly, obesity-derived inflammation is potentially driven by the action of certain adipokines, such as leptin." (PMID 36555171, 2022). "Moreover, WBV affects the signaling pathways of obesity-related hormones, including insulin and leptin." (PMID 35456575, 2022). "Furthermore, leptin levels have been observed to be higher in postmenopausal women with hypertension, and obesity has been attributed to alterations in the leptin-activated melano cortical pathway." (PMID 35937205, 2022). "Obesity, a frequent comorbidity of OSA, causes hyperleptinemia and leptin resistance." (PMID 36726470, 2022). "This is due to obesity, which activates an organ-specific leptin-resistant state." (PMID 36422274, 2022). "Circulating levels of insulin and leptin are high in obesity." (PMID 35406618, 2022). "High levels of circulating leptin and free fatty acids, low serum levels of ghrelin and adiponectin, and hyperinsulinemia are the main mechanisms involved in the genesis of sympathetic hyperactivity in obesity." (PMID 35019127, 2022). "Some models include leptin, leptin resistance, and leptin receptors to understand obesity." (PMID 35480480, 2022). "Moreover, our study strengthened these findings by further genetic associations with numerous obesity-related metabolic traits (e.g., rs10195252 with FPG, leptin and HbA1c; rs6738627 with T2D, FPG, leptin, TG, and adiponectin)." (PMID 35955692, 2022). "Leptin and adiponectin are regulated in asthma by obesity-dependent and -independent mechanisms." (PMID 35807067, 2022). "In support of a model, where leptin and adiponectin have opposing roles in driving pro-inflammatory and anti-inflammatory B cell functions, respectively, B cells from individuals living with obesity have reduced pAMPK compared to lean individuals." (PMID 35960996, 2022). "We observed that pre-pubertal children with obesity and with low z-scores of circulating leptin levels had significantly higher triglyceride, fasting insulin and fasting c-peptide levels compared to children with normal z-scores of circulating leptin levels." (PMID 35677722, 2022). "Obesity is heterogeneous in its phenotype, and it is the accumulation of excess adipose tissue viscerally associated with insulin resistance, dyslipidaemia, inflammation, hypothalamic leptin resistance and gliosis that underpins the functional hypogonadism of obesity." (PMID 35834069, 2022). "While much is known about obesity in the context of other solid tumors, the impact of obesity on lung cancer is underexplored, with proposed mechanisms, including alterations of tumor metabolism and leptin-mediated immune modulation." (PMID 36289552, 2022). "Compared with the studies that referred to leptin and diabetes or obesity, very few studies were associated with leptin and asthma, and the mechanistic basis for the role of leptin in asthma has not been established completely." (PMID 36551211, 2022).
Obesity (continued). "High-fat diet-induced obesity was related either to the failure of leptin synthesis and secretion." (PMID 36612600, 2022). "Our results may be attributed to insulin resistance, the etiology of obesity, and an increased plasma leptin level." (PMID 36530622, 2022). "Studies relating to animal models support the role of leptin in obesity asthma." (PMID 36551211, 2022). "The factors related to obesity that negatively influence bone mass are mainly associated with an increase in the percentage of fat mass since obesity is a proinflammatory state that is associated with the secretion of a series of cytokines (IL-6, TNF-α) and adipokines (adiponectin, leptin...)." (PMID 35458178, 2022). "Leptin inhibits appetite and food intake, stimulates energy expenditure, and also has pro-inflammatory effects contributing to the low-grade chronic inflammation by enhancing the TNF-α and IL-6 production and vice versa TNF-α stimulated leptin secretion from adipocytes that induces obesity." (PMID 36297569, 2022). "Similarly, another possible outcome of this study is to understand the leptin regulation behavior in women with obesity against their matched healthy subjects." (PMID 35480480, 2022). "Leptin levels were higher while adiponectin was lower in asthmatics with obesity." (PMID 35889925, 2022). "Therefore, we dedicate a chapter specifically to the putative effects of leptin signalling dysregulation on mitochondrial function in oocytes during obesity." (PMID 36855701, 2022). "The relationship between leptin, leptin receptor and obesity." (PMID 36551995, 2022). "Abnormal leptin levels at the end of pregnancy are positively correlated with neonatal obesity." (PMID 36615730, 2022). "In addition, the expression of ER stress markers are enhanced in obesity models and ER stress is related to the development of leptin resistance, which is an obesity inducer." (PMID 36187475, 2022). "In many population-based studies, low birth weight also resulted in an increase in obesity-related problems such as leptin resistance due to the elevated hormone levels from the catch-up growth phase, T2DM, high blood pressure, cardiovascular disease, and insulin resistance." (PMID 35328862, 2022). "The leptin hormone increases energy expenditure, which plays a protective role against obesity." (PMID 36187475, 2022). "Finally, leptin and GLP-1 were positively associated with obesity (OR = 1.367, and 95% CI = 1.117–1.672; OR = 1.239, and 95% CI = 1.018–1.508, respectively)." (PMID 35334929, 2022). "Leptin might be responsible for the exacerbated mineralocorticoid receptor signaling in obesity-related HFpEF, possibly through impaired calcium handling and relaxation in the heart." (PMID 36579524, 2022). "Similar to leptin, adiponectin is also correlated with obesity." (PMID 36578551, 2022). "Furthermore, the studies and the scientific evidence presented seem to indicate that reducing inflammation can act on the pathways involved in leptin resistance, producing an improvement in leptin or its sensitivity and obtaining favourable results on obesity." (PMID 35563589, 2022). "In particular, knockouts of different genes in the leptin-melanocortin feedback loop that signals satiety in the hypothalamus generally result in obesity, but although the neural circuits are unidirectional, both anabolic and catabolic effects have been observed in bone." (PMID 36342465, 2022). "It is speculated that altered expression of specific genes might influence the responsiveness of ligamentum flavum cells to the obesity-induced persistent stimulus, such leptin." (PMID 35712246, 2022). "All of these suggest that gut microbiota modulation could be a novel therapeutic target in obesity focusing on leptin signaling." (PMID 36225863, 2022).
Obesity (continued). "Very little is known about the immunomodulatory effects of leptin in pregnancies with maternal obesity, although it has been suggested that pre-gravid high circulating leptin levels in women with obesity prime the placental inflammation observed in these pregnancies." (PMID 35348641, 2022). "Therefore, the role of leptin in the progression of obesity complications needs to be further investigated." (PMID 35409324, 2022). "Moreover, several other obesity-related inflammatory factors, including IL-17, leptin, adiponectin, NLRP3 inflammasome, and TLR-4 have been implicated in the pathogenesis of lung disease." (PMID 35360873, 2022). "Recent findings have shown that white adipose tissue is responsible for the secretion of adipokines, such as leptin and adiponectin, which are closely related to metabolic diseases such as obesity, insulin resistance, and diabetes and play an important regulatory role in bone diseases." (PMID 35453776, 2022). "Notably, leptin treatment (6 μg/g) was able to increase interscapular BAT temperature in control, diet-induced obese and ob/ob mice, suggesting that thermogenic response to leptin is intact in the obesity models studied in spite of systemic leptin resistance." (PMID 34523036, 2022). "Leptin might play a role in β-cell compensatory insulin hypersecretion, particularly in the state of leptin resistance that occurs in obesity." (PMID 35628332, 2022). "Celastrol is a potent leptin-sensitizing anti-obesity agent when administered to adult animals." (PMID 35684076, 2022). "We therefore hypothesized that mediators of obesity such as high leptin levels might influence endothelial responses to SARS-CoV-2 infection." (PMID 35837388, 2022). "In obesity, oxidative stress linked with alteration of the immune system and with ultimate aberrant cell signaling, stimulated cell growth and angiogenesis is promoted via enhanced inflammatory factors and adipokines (TNF, leptin, IL-1β, and IL-6)." (PMID 35628513, 2022). "Among these, leptin, visfatin, and resistin have a pro-inflammatory role decreasing the insulin sensitivity and inducing the development of chronic complications; on the contrary, adiponectin shows anti-inflammatory properties in the context of obesity." (PMID 36386923, 2022). "In dogs, obesity appears to induce excessive production of leptin, as observed in humans." (PMID 36262532, 2022). "The aim of this study is to explore the relationship between several peripheral obesity-related biomarkers (i.e., ghrelin, IR, and leptin/adiponectin ratio) and eating styles (i.e., external, emotional, and restrained) in a Spanish sample of obese children and adolescents." (PMID 35057485, 2022). "Strikingly, treatment with EA for only 2 weeks reduced the obesity-elevated leptin and insulin levels by 69.3% and 58.5%, respectively, in obese mice, which is likely due to improved obesity and insulin resistance consistent with previous findings in this mouse model." (PMID 36386896, 2022). "Mutations in leptin and LEPR genes have been reported to cause obesity in human and animal models." (PMID 35650533, 2022). "Leptin resistance, or its inability to modulate energy intake and expenditure is common in obesity." (PMID 35721764, 2022). "Moreover, mice lacking RhoA in hypothalamic tyrosine hydroxylase neurons showed increased sensitivity to ghrelin and decreased sensitivity to leptin, resulting in increased food intake and development of obesity." (PMID 35769086, 2022). "Furthermore, the combined deletion of PTP1B and TCPTP in neuronal and glial cells or POMC neurons results in an improvement in leptin sensitivity as well as a decrease in diet-induced obesity." (PMID 35563589, 2022). "We and other groups have reported that ER stress may play a role in inducing leptin resistance, and could affect the result in the development of obesity." (PMID 36512575, 2022).
Obesity (continued). "Moreover, a positive correlation was observed between LRG1 and other obesity markers, including HsCRP, leptin, and chemerin." (PMID 35955698, 2022). "Clearly, obesity and hormones such as leptin play complex roles in the TME." (PMID 35039633, 2022). "We found that HJJPD reduces hyperleptinemia, alleviates chronic inflammatory response, improves leptin resistance of obese mice, and plays a role in treating simple obesity by activating the LEP-mediated JAK2-STAT3 signaling pathway in liver and adipose tissue." (PMID 35529938, 2022). "It is not clear, if gut microbiome composition changes are driven by a decrease in leptin action, as a consequence of hyperphagia, physiological modifications associated with obesity, or other leptin actions independent of food intake and adiposity." (PMID 36225863, 2022). "The concept of leptin resistance may explain the paradoxically elevated leptin levels in obesity, notably through impaired transportation of leptin through the blood-brain barrier and the decreased hypothalamic leptin receptor expression." (PMID 35334929, 2022). "The absence of leptin is the cause of a pathological condition characterized by severe obesity, hyperinsulinemia and dyslipidemia." (PMID 35743665, 2022). "In general, our study showed that chitosan supplementation can improve cardiometabolic parameters (anthropometric indicators of obesity and lipid and glycemic markers) and appetite-related hormones (adiponectin, leptin, and NPY) in adolescents with overweight or obesity." (PMID 36064382, 2022). "Serum leptin levels reflects one’s degree of obesity and can affect vitamin D levels." (PMID 35721764, 2022). "Additionally, the influence of obesity on the concentration of selected blood parameters, i.e., troponin, ghrelin and leptin, in horses was assessed." (PMID 35327129, 2022). "Finally, the leptin-melanocortin pathway has been extensively studied in animal models as a driving factor of hypertension in obesity." (PMID 36293177, 2022). "DIO mice develop hyperleptinemia due to excess adipose tissue accumulation; however, they do not respond to the anorectic effect of administered leptin due to obesity-associated leptin resistance." (PMID 35323110, 2022). "However, leptin concentration in the CSF of individuals with obesity was found to be only 30% higher than lean participants, which means a higher leptin CSF/serum ratio in lean participants." (PMID 36313760, 2022). "Therefore, changes in leptin levels during obesity levels can potentially affect oocyte fatty acid oxidation and energy provision during critical phases of oocyte growth and developmental competence." (PMID 36855701, 2022). "To do so, we investigated the effect of leptin on the pathophysiology mechanisms observed on an LPS-induced model of PTL, using a reported co-culture model of human primary myocytes and macrophages, in which cells were stimulated with LPS to mimic inflammation and leptin as a feature of obesity." (PMID 35326405, 2022). "The literature suggests that leptin may be the link between obesity and dementia through the development of inflammation." (PMID 35563589, 2022). "Moreover, in adult populations the ratio has proven a more accurate marker of obesity-related complications than adiponectin or leptin alone." (PMID 34977280, 2022). "One example is using serum leptin as an additional anthropometric index to classify obesity." (PMID 35628271, 2022). "Sulforaphane (SFN) reduces obesity by improving leptin action." (PMID 35323110, 2022). "A subgroup analysis of sex according to obesity status showed that in the dominant model, the associations between LEP polymorphisms and leptin levels were significant only among obese women (rs2167270, 33.25 ± 27.83, p = 0.025; rs7799039, 33.23 ± 26.85, p = 0.008)." (PMID 36293132, 2022).
Obesity (continued). "In turn, hypothalamic expression of PTPs has been found to be increased in obese animals, and selective ablation of these proteins partially prevents diet-induced obesity and improves leptin sensitivity, providing a demonstration of their role in the onset of leptin resistance." (PMID 34523036, 2022). "We propose that peripheral leptin inhibits bone resorption in obesity." (PMID 36173650, 2022). "Therefore, our study aimed at examining the effects of gut microbiota in energy homeostasis and contribution to obesity development, specifically in leptin-related central pathways." (PMID 36233056, 2022). "Thus, this study aimed to examine the associations between FTO (rs9939609), FABP2 (rs1799883), LEP (rs2167270), LEPR (rs1137101), and MC4R (rs17782313) polymorphisms and obesity-related traits." (PMID 35627568, 2022). "Although it is known that the adipokines, resistin, and leptin might inhibit the formation of adipose tissue, further research is necessary to define its protective effect against obesity and insulin resistance in breastfed infants." (PMID 35225882, 2022). "PAT secretes leptin and adiponectin that act to prevent neonatal obesity." (PMID 36012601, 2022). "There is an inverse correlation between adiponectin and leptin in obesity." (PMID 36430738, 2022). "Leptin with adipose-tissue-derived angiotensin II can promote obesity-related hypertension." (PMID 35056647, 2022). "Considering that the activation of LepR in hypothalamic neurons reduces food intake and may increase energy expenditure and fat oxidation, leptin sensitizing therapies will likely produce robust beneficial effects in the prevention and treatment of obesity." (PMID 35742928, 2022). "This confirms that obesity, whether induced by HFD, or leptin deficiency drives elevation in Atp6v0a1." (PMID 36042358, 2022). "In children, a relationship between obesity and asthma has also been found via high leptin levels and a low adiponectin concentration in blood, suggesting that those adipokines, together with the BMI, may be potential predictive biomarkers for asthma." (PMID 36613991, 2022). "Concerning genes carried by autosomal chromosomes, the studies of extreme forms of early onset obesity in humans identified genes with major influence on the central nervous system in the control of adiposity including the leptin-melanocortin pathway (LEP, LEPR, POMC, PCSK1, MC4R)." (PMID 36289874, 2022). "Likewise, it also illustrates how obesity can be a detrimental factor for patients diagnosed with cancer, due to metabolic effects and also leptin-mediated direct effects." (PMID 35628271, 2022). "The analysis of the impact of hypermethylation of 20 genes related to obesity on renal carcinogenesis and prognosis revealed that genes of neuropeptide Y, leptin, and leptin receptor were considerably more hypermethylated compared to normal adjacent parenchyma tissue (p < 0.0001)." (PMID 35328822, 2022). "However, despite serum leptin levels being elevated in direct proportion to the amount of body fat, the efficacy of its anorexic effect is decreased in obesity." (PMID 36131285, 2022). "Therefore, under conditions of altered leptin signalling such as in obesity, the metabolism in ovarian somatic cells, as well as the gamete, are susceptible to dysregulation." (PMID 36855701, 2022). "Lack of leptin is then associated with increased intake, proinflammatory activity, and obesity in the offspring." (PMID 35391836, 2022). "Leptin sensitivity is considered to be directly related to obesity and adipose tissue volume." (PMID 36117520, 2022). "Leptin is a pro-inflammatory adipokine that has been shown to contribute to the local and systemic inflammatory milieu in obesity via a mechanism involving the activation of pro-inflammatory cells, the stimulation of the Th1 cell response, and the production of pro-inflammatory cytokines." (PMID 35409299, 2022).